IGF2 (insulin like growth factor 2)
Diseases named in the same sentence as IGF2 in open-access papers (continued):
Sharing a sentence is not in itself a finding about the gene and the disease.
Alzheimer disease (26 papers, 2014 to 2026). A progressive, neurodegenerative disease characterized by loss of function and death of nerve cells in several areas of the brain leading to loss of cognitive function such as memory and language. "In the DisGeNET database, LRP6, F11, CXCL10, TCF4 and IGF2 are identified as the top five genes associated with Alzheimer's disease, with association scores of 0.989, 0.981, 0.953, 0.938 and 0.914, respectively." (PMID 38350848, 2024). "Insulin‐like growth factor 2 (IGF2) is a neurotrophic peptide that is implicated in memory function and declines in Alzheimer's disease (AD)." (PMID 36971212, 2023). "IGF2 upregulation can promote neurogenesis and synapse formation against oxidative stress, suggesting a potential neuroprotective role for miR-483-5p in Alzheimer’s disease." (PMID 37489457, 2023). "Specific DNAme changes are also observed in atherosclerosis and cardiovascular disease (e.g., ABCG1), metabolic disorders (e.g., ANKRD26, IGF2), Alzheimer’s disease, and other nervous system disorders (e.g., IGF2)." (PMID 38136557, 2023). "The expression of insulin, IGF1, IGF2 and its receptors and downstream substrates are reduced in the brain of Alzheimer’s disease (AD) patients." (PMID 38042807, 2023). "In contrast, virus-mediated overexpression of IGF-2 rescues the frequency of miniature EPSCs in the CA1 region in a mouse model of Alzheimer Disease as compared to control mice." (PMID 38298376, 2023). "MiR-483-5p is co-upregulated with its host gene IGF2 in the cerebrospinal fluid of patients with Alzheimer’s disease." (PMID 37489457, 2023). "Patients with Alzheimer’s disease (AD) have decreased IGF-2 expression (compared with control subjects) in some brain regions, as was demonstrated in a number of studies using post-mortem brain samples." (PMID 33673334, 2021). "Administration of IGF2 rescues spine formation and excitatory synaptic function in the hippocampus of a mouse model of Alzheimer’s disease." (PMID 27083047, 2016). "In addition, IGF2 has shown the neuroprotective functions in several neurodegenerative diseases, such as Alzheimer’s disease, Parkinson’s disease, amyotrophic lateral sclerosis, and spinal muscular atrophy." (PMID 40713750, 2025). "The expression of IGF2, a neurotrophic factor, is reduced in people with Alzheimer’s disease (AD)." (PMID 39830039, 2024). "Reduced insulin-like growth factor 2 (IGF2) levels in Alzheimer’s disease (AD) may be the mechanism relating age-related metabolic disorders to dementia." (PMID 36739453, 2023). "In the context of psychiatric disorders, IGF-2 peripheral levels have been previously studied in schizophrenia and in neurodegenerative disorders that impair memory or cognitive status, such as Alzheimer’s disease, Huntington’s disease and Parkinson’s disease." (PMID 37894932, 2023). "A number of studies performed on rodents suggest that insulin-like growth factor 2 (IGF-2) or its analogs may possibly be used for treating some conditions like Alzheimer’s disease, Huntington’s disease, autistic spectrum disorders or aging-related cognitive impairment." (PMID 33673334, 2021). "Furthermore, increasing IGF2 levels in the hippocampus of Alzheimer’s disease model mice rescues cognitive, cellular and synaptic impairments, suggesting that IGF2 might represent a target for regulating cognitive functions in neuropsychiatric diseases." (PMID 26495851, 2015). "Furthermore, we report that IGF2 expression decreases in the hippocampus of patients with Alzheimer's disease, and this leads us to hypothesize that increased IGF2 levels may be beneficial for treating the disease." (PMID 25100745, 2014). "Researchers from our group have previously studied the roles of both IGF-2 and IGFBP-7 in schizophrenia, as well as in the extinction of fear memories in mouse models and as possible targets for treatment in Alzheimer’s disease." (PMID 37894932, 2023).
Alzheimer disease (continued). "Members of our group have previously investigated the role of IGF-2 and IGFBP-7 in the extinction of fear memories and as a potential drug target in Alzheimer’s disease (AD)." (PMID 36076984, 2022). "Although studies show that IGF-2 can increase memory in healthy mice and improve memory in neurodegenerative diseases such as Alzheimer disease, we could not find any study about the effect of IGF-2 on neuroinflammation diseases and acute brain injuries such as stroke or trauma." (PMID 34466449, 2018). "Hence, IGF2 and, to a lesser extent, IGF1 may be effective treatments for Alzheimer's disease." (PMID 25100745, 2014).
glioblastoma (26 papers, 2012 to 2026). The most malignant astrocytic tumor (WHO grade IV). "We demonstrate a unidirectional regulatory hierarchy wherein NTRK1 transcriptionally governs IGF2 to amplify proteotoxic stress, a mechanism previously documented in glioblastoma but newly implicated in pain neuroscience." (PMID 40722704, 2025). "The relevance of IGFBPs in treatment response has been additionally reported in glioblastoma, where IGF2/IGF1R expression is associated with poor response to temozolomide." (PMID 33673232, 2021). "IGF2 has also been suggested to influence the adult brain under pathological conditions, as the uncontrolled proliferation that is characteristic of glioblastoma has been linked to elevated CSF–IGF2 concentration." (PMID 26369386, 2015). "This paradigm, observed in glioblastoma but previously unreported in pain neuroscience, manifests maladaptively in CPSP as NTRK1-induced IGF2 overexpression exacerbates ER stress, creating a pathogenic feedforward loop." (PMID 40722704, 2025). "An example is the structural change in the lincRNA small nucleolar RNA host gene 25 (SNHG25), which overlaps the binding site of protein insulin like growth factor 2 mRNA binding protein 2 (IGF2BP2) in glioblastoma multiforme." (PMID 41387767, 2025). "In glioblastoma, miR-873-5p repressed IGF2 mRNA-binding protein 1 (IGF2BP1) expression to suppress glioblastoma tumorigenesis." (PMID 34497766, 2021). "IGF2BP3 can also induce cell proliferation and invasiveness via post-transcriptional regulation of IGF2; the resulting IGF2 then activates oncogenic phosphatidylinositcol 3-kinase/mitogen-activated protein kinase (PI3K/MAPK) pathways in glioblastomas." (PMID 25216519, 2014). "Further more, the insulin-like growth factor 2 (IGF2)-p55PIK interaction involved in promoting the growth of a subset of proliferative glioblastomas that lack EGF receptor amplification." (PMID 23509792, 2013). "Knockdown of PIK3R3 inhibits IGF2-induced cell growth in glioblastoma multiforme and induces apoptosis in ovarian cancer cells." (PMID 22876838, 2012). "It is worth noting that a small subset of glioblastomas with elevated IGF2 expression may be prognostically relevant." (PMID 40429889, 2025). "Similarly, IGF2 is expressed by ChP and can be detected at higher levels in the CSF of glioblastoma patients." (PMID 40429889, 2025). "Activate IGF2/PI3K/AKT signaling pathway promotes glioblastoma multiforme progression." (PMID 29212217, 2017). "Activating IGF2/PI3K/AKT pathway promotes glioblastomas multiforme progression." (PMID 29212217, 2017). "This study aims to investigate the mechanism underlying IGF2 mRNA-binding protein 2 (IGF2BP2) and long noncoding RNA DANCR in etoposide resistance of glioblastoma (GBM) cells." (PMID 35141227, 2021). "The overexpression of IGF2BP2 has also been shown to promote the development of glioblastoma multiforme by activating the IGF2/phosphoinositide 3-kinase (PI3K)/Akt pathway, thereby making glioblastoma resistant to temozolomide therapy." (PMID 35919812, 2022). "In glioblastoma cells, the IGF2BP2/IGF2/Akt axis promoted cell motility and EMT, as demonstrated by increased mRNA and protein expression of vimentin and N-cadherin." (PMID 33673232, 2021). "In terms of cancer, IGF2 mRNA-binding protein 2 (Imp2) regulates the activity of IGF2, which further activates PI3K/AKT signaling to promote glioblastoma (GBM) malignancy." (PMID 31770673, 2019). "Another study reported that the Insulin-like growth factor 2 (IGF2) and p55PIK are overexpressed in more proliferative glioblastomas." (PMID 23509792, 2013). "In glioblastoma, IGF2PB3 may promote tumor growth by increasing the secretion of IGF2." (PMID 37156775, 2023). "In addition, we demonstrated that exogenous IGF2 induced ERK1/2 phosphorylation in glioblastoma cells (U-87MG), but not in neuroblastoma cells (IMR-32)." (PMID 26580597, 2015).
glioblastoma (continued). "Through paracrine IGF2/IGF-1R signaling, IGFBP6 regulates the growth of chemoresistant glioblastoma, which is produced by scilicet chemosensitive tumor cells, and is secreted, which slows the evolution of GBM." (PMID 36865549, 2023).
Hyperglycemia (26 papers, 2011 to 2025). An increased concentration of glucose in the blood. "We confirmed the existence of alteration in DNA methylation in umbilical cord blood exposed to intrauterine hyperglycemia and reported a functional role in regulating gene associated with insulin-like growth factor 2/H19." (PMID 26840070, 2016). "We confirmed the existence of alteration in DNA methylation in umbilical cord blood exposed to intrauterine hyperglycemia and reported a functional role in regulating gene associated with IGF2/H19." (PMID 26840070, 2016). "Positive correlations between maternal IGF-2 concentration and weight gain during pregnancy in the study group could be caused by increased secretion from adipose tissue in response to hyperglycemia." (PMID 33053704, 2020). "The level of methylation of the IGF2/H19 locus in GDM placentas was shown to correlate with the level of intrauterine hyperglycemia, as well as with the birth weight of the neonates." (PMID 39765830, 2024). "In conclusion, we reported a previously unrevealed function of A. muciniphila gavage in protecting mice from STZ‐induced hyperglycemia and atrophy by promoting intestinal IGF2 secretion." (PMID 39429872, 2024). "This study confirms that intrauterine hyperglycemia exposure will result in altered DNA methylation of the imprinted gene IGF2/H19 in cord blood, which in turn affects gene expression." (PMID 39273309, 2024). "Intrauterine hyperglycemia also decreases the expression of H19 and Igf2 in mouse pancreatic islets of F2 generation offsprings of gestational diabetes mellitus (GDM) mice." (PMID 28814771, 2017). "The relationship between altered methylation level of specific sites of IGF2 and H19 and hyperglycemia should be investigated in depth in animal and cell studies." (PMID 26840070, 2016). "A recent study showed that streptozotocin (STZ)-injected mice exhibited increased A. muciniphila abundance, and that gavage of heat-killed A. muciniphila protected mice from STZ-induced hyperglycemia and atrophy by promoting intestinal insulin-like growth factor 2 (IGF2) secretion." (PMID 39796314, 2024). "The therapeutic use of anti-IGF-2 neutralizing antibodies may offer better tolerability by avoiding hyperglycemia, a common side effect of small molecule IGF1R inhibitors, due to cross-reaction with the Insulin Receptor." (PMID 36809604, 2023). "Together, these results demonstrate that lack of Igf2 expression in pancreatic β-cells is detrimental in obese females with congenital leptin deficiency, leading to exacerbated hyperglycaemia in young adult life." (PMID 33833312, 2021). "Intrauterine hyperglycemia may affect expression of IGF2/H19 through altering methylation level of IGF2/H19." (PMID 26840070, 2016). "Therefore, it may be the case that hyperglycemia also induces damage to vestibular hair cells and alterations in IGF-2, GFAP, and Nnat expression in the vestibular nuclei of mice fed HSHFD." (PMID 32012199, 2020).
neuroblastoma (25 papers, 2005 to 2025). Neuroblastoma (NB) is the most common solid, extracranial childhood tumor. "In clinical neuroblastoma chromogranin A immunoreactivity is associated with tumor hypoxia, but with less dynamic range than IGF2 expression." (PMID 20862257, 2010). "In particular, we were able to demonstrate that iLIN28B neuroblastoma cells can stimulate the migration of endothelial cells and the formation of mesh structures through the release of IGF2." (PMID 40679030, 2025). "Here, we describe the LIN28B/IGF2 signaling pathway as a novel mechanism that supports tumor angiogenesis in LIN28B‐dependent neuroblastoma." (PMID 40679030, 2025). "In order to explore the advanced effects of IGF2 on the one critical characteristic, mHTT aggregate, in HD, we delivered the G84Q, used as mHTT, and IGF2 constructs into the N2a neuroblastoma cells, and examined the profiling of mHTT aggregates." (PMID 40713750, 2025). "Eosinophils were first identified in neuroblastoma in the 1990s when a study of 21 tumors revealed their presence, along with insulin-like growth factor 2 (IGF-2) expression in these cells." (PMID 38087370, 2023). "Attempting to decipher how MYCN expression escapes elevated expression of inhibitory miRNAs, we present evidence that RNA-binding proteins like the IGF2 mRNA binding protein 1 reduce miRNA-directed downregulation of MYCN in neuroblastoma." (PMID 34026620, 2021). "These experiments are consistent with hypoxic expression of NESP55 and of IGF2 representing markers for chromaffin differentiation in neuroblastoma tissue." (PMID 20862257, 2010). "In neuroblastoma IGF2 expression is an excellent marker for hypoxia, with more than 100-fold induction reported." (PMID 20862257, 2010). "In our previous characterization of the hypoxic phenotype in neuroblastoma we employed two markers, IGF2 and chromogranin A." (PMID 20862257, 2010). "Together with IGF2 expression, this observation provides some independent support for a neuroendocrine tumor phenotype of hypoxic neuroblastoma cells in view of the chromaffin-specific expression of HIF2α and IGF2 in fetal tissues." (PMID 20862257, 2010). "Notably, LOI of IGF2 is an early initiating event in the development of ileal neuroendocrine tumors, and our results show biallelic expression of IGF2 isoforms in cell lines from other neuroendocrine tumors (neuroblastoma and SCLC)." (PMID 40414875, 2025). "Studies comparing HIF protein expression with the expression of hypoxia driven genes at the cellular level in tumor sections have shown that HIF-1α/HIF-2α expression is not always congruent with an expression of established hypoxia driven genes such as TH and IGF-2 in neuroblastoma." (PMID 33467498, 2021). "However, growth factor signaling has been shown to regulate HIF1α at both the transcriptional and translational level, and HIF2α transcription in hypoxic neuroblastoma cells is regulated by IGF-2." (PMID 26849233, 2016). "This may result in gain of function of the genes in this region, as for example, IGF2, which is known to induce neuroblastoma cell proliferation." (PMID 17327916, 2007). "The IGF1R pathway is aberrantly activated by autocrine and paracrine signaling loops in neuroblastoma tumors through the release of IGF1 and IGF2, ligands for IGF1R, from the neuroblastoma and stromal cells within the tumor." (PMID 39001383, 2024). "Previous data from our laboratory have shown that sAPPα up-regulates the transcripts of IGF2 and IGFBP2 transiently after 30 min exposure in a human neuroblastoma SH-SY5Y cell culture model." (PMID 37108327, 2023). "In neuroblastoma, it has been reported that MAML3 over-expression increased IGF2 transcription independently from Notch, and this mediated IGF1R activation and AKT signaling, resulting in an increased cell proliferation." (PMID 35163581, 2022).
neuroblastoma (continued). "More specifically, neuroblastoma cells undergo a decrease in both cell proliferation and tumorigenic potency as a result of exogenous IGFBP-6 expression as IGFBP-6 sequesters IGF-2 preventing a mitogenic response in tumor cells." (PMID 29387091, 2017). "Although the chromaffin tumor phenotype in neuroblastoma is easily revealed by analyzing expression of NESP55 and IGF2, the corresponding morphological features are relatively inconspicuous." (PMID 20862257, 2010).